MEG3 (maternally expressed 3)
Diseases named in the same sentence as MEG3 in open-access papers (continued):
Sharing a sentence is not in itself a finding about the gene and the disease.
pulmonary fibrosis (8 papers, 2021 to 2025). Chronic progressive interstitial lung disorder characterized by the replacement of the lung tissue by connective tissue, leading to progressive dyspnea, respiratory failure, or right heart failure. "LncRNA MEG3 reduced collagen formation in pulmonary fibrosis by suppressing the transforming growth factor-β1 and PI3K/AKT pathway." (PMID 37367427, 2023). "The overexpression of MEG3 in the lung epithelial cells of the idiopathic pulmonary fibrosis (IPF) model disrupted their epithelial differentiation and promoted the EMT process." (PMID 35890132, 2022). "A study of MEG3 expression in idiopathic pulmonary fibrosis using scRNA-seq demonstrated that MEG3 regulates the differentiation of bronchial cells through diverse mechanisms, including through YAP1, NOTCH, and SOX2 signaling." (PMID 36231143, 2022). "In a previous publication, MEG3 is also expressed at higher levels in epithelial cells separated from patients with idiopathic pulmonary fibrosis." (PMID 34558385, 2021). "In a publication, MEG3 is abundant in idiopathic pulmonary fibrosis and plays as a mediator in the development of this lung disorder." (PMID 34558385, 2021). "They discovered that NiO NPs-induced rat pulmonary fibrosis was accompanied by the epithelial–mesenchymal transition (EMT) occurrence and MEG3 down-regulation in rat lung tissues." (PMID 40087769, 2025). "In this study, acute pulmonary inflammation in rats also led to dysbiosis of the lung microbiome.NiO NPs induce lung fibrosis in rats by activating TGF-β1, a process that is accompanied by EMT and downregulation of MEG3 in lung tissue." (PMID 40087769, 2025). "Overexpression of DNMT1, knockdown of lncRNA MEG3, autophagy inhibitor or ERK/p38 signaling pathway inhibitors reversed the positive effect of IL-27 in a lung fibrosis model in vitro." (PMID 36869378, 2023). "Their results indicated that MEG3 inhibited NiO NPs-induced collagen deposition by regulating transforming growth factor-β1 (TGF-β1)-mediated EMT process, which may provide some clues for insighting into the mechanisms of NiO NPs-induced pulmonary fibrosis." (PMID 40087769, 2025).
renal cell carcinoma (8 papers, 2014 to 2025). "On the other hand, in renal cell carcinoma (RCC) cells ST3GAL1 is positively regulated by MEG3, a lncRNA with a tumor suppressor activity." (PMID 33921986, 2021). "lncRNA MEG3 induces renal cell carcinoma (RCC) cells apoptosis by activating the mitochondrial pathway." (PMID 28835257, 2017). "Furthermore, the expression of MEG3 has been studied in various types of renal cell carcinoma (RCC), including clear cell RCC (ccRCC) and papillary RCC (pRCC)." (PMID 40242248, 2025).
breast tumor (7 papers, 2015 to 2025). "Herein, normal like (NL) breast tumors had significantly higher expression of MEG3 with a p-value of 0.0003 (left)." (PMID 32612992, 2020). "SP was upregulated while miR-506 and MEG3 were downregulated in breast tumor tissue compared to adjacent normal breast tissues." (PMID 30386180, 2018). "Conversely, the expression of MEG3 (Maternally Expressed 3) is lower in breast tumors than in normal breast tissues, and the expression level of MEG3 was negatively correlated with histological tumor grade, and MEG3 downregulation correlated with poor OS." (PMID 30545127, 2018). "The RT-qPCR results showed that miR-506 and MEG3 levels were significantly lower (about half) in breast tumor tissues than in adjacent normal tissues." (PMID 30386180, 2018). "In light of our results showing high expression of MEG3 in breast stromal tissue, and uncertainty that measured MEG3 expression in the normal-like subgroup is representative of the primary tumor, we omitted NL breast tumors from the survival analysis." (PMID 32612992, 2020). "We have evaluated the expression of MEG3 in clinically well-defined breast tumors." (PMID 32612992, 2020). "We next evaluated the expression of four candidate lncRNAs in 50 paired breast tumor and normal tissue samples, confirming significant downregulation of ADAMTS9-AS2, HAND2-AS1, HOTAIRM1, and MEG3 (P < 0.001)." (PMID 40350996, 2025). "Furthermore, TNMplot database also pinpointed a negative correlation between MEG3 and CXCR4 expression in breast tumor samples." (PMID 40548301, 2025).
cognitive decline (7 papers, 2020 to 2025). "MEG3 has also been suggested to play a role in Parkinson’s disease where its expression is downregulated, acting as a biomarker for cognitive decline and disease stage." (PMID 36869839, 2023). "It has been reported that the relative expression level of Meg3 in PD patients is lower than that in the healthy population, while Apoe has an impact on the cognitive decline of PD." (PMID 36142685, 2022). "A previous investigation revealed that upregulating the lncRNA MEG3 may reverse cognitive decline and lessen neuronal damage." (PMID 40869265, 2025). "For example, MEG3, which shows a fold change of − 0.6 (± 0.21) in the GSE173955 dataset, has been reported to significantly improve AD-associated cognitive decline in AD mice models." (PMID 39143264, 2024). "In summary, the expression of lncRNA MEG3 in the plasma of PD patients was downregulated compared to that of healthy control subjects, and its expression level was closely related to the aggravation of non-motor symptoms, cognitive decline, and PD stage." (PMID 33329296, 2020).
immune thrombocytopenic purpura (7 papers, 2017 to 2023). "Expression of MEG3 has been shown to be elevated in CD4 + T cells of patients with immune thrombocytopenic purpura." (PMID 34373511, 2021). "MEG3 expression is upregulated in CD4+ T cells of patients with immune thrombocytopenic purpura and this enhances the immune imbalance of Treg/Th1723." (PMID 31729423, 2019). "MEG3 inhibits microRNA-125a-5p expression and induces immune imbalance of Treg/Th17 in immune thrombocytopenic purpura." (PMID 30546835, 2018). "LncRNA MEG3 also was found to function as a ceRNA of several miRNAs, for instance, miR-125a-5p in immune thrombocytopenic purpura, miR-770-5p in Hirschsprung’s disease." (PMID 29255591, 2017). "Furthermore, in immune thrombocytopenic purpura, MEG3 was involved in the regulation of immune imbalance through inhibiting miR-125a-5p, though the regulatory role of MEG3/miR-125a-5p in the proliferation of VSMCs has not been reported." (PMID 30156956, 2019). "MEG3, a lncRNA expressed in CD4+ T cells, contributes to the imbalance of Tregs/Th17 ratio in patients with immune thrombocytopenic purpura." (PMID 30319599, 2018). "Additionally, the overexpressed lncRNA MEG3 interacted with miR-125a-5p and suppressed its expression, whereas the downregulation of MEG3 increased the expression of FOXP3 via miR-125a-5p in the CD4+ T cells in immune thrombocytopenic purpura." (PMID 37709486, 2023).
oral cancer (7 papers, 2018 to 2024). "Decreased expression of MEG3 is associated with a poor prognosis in oral cancer, which consistent with the observation that MEG3 inhibits OSCC cell growth and metastasis by suppressing Wnt/β-catenin signaling." (PMID 30069008, 2018). "In oral cancer, hypermethylation occurs on the miR-379/656 cluster promoter, where the genomic imprint for the non-coding RNA Meg3 differential methylation region (Meg3-DMR) also inhibits down-stream noncoding RNA and microRNA cluster expression." (PMID 33673471, 2021). "Furthermore, using oral cancer data from The Cancer Genome Atlas (TCGA), we observed that MEG3 was positively correlated with α-SMA and COL1A1." (PMID 35890132, 2022). "2/miR-328, LncRNA MEG3/miR‐548d‐3p, and LINC00958/miR-4306 are examples of circRNAs/miRNAs and lncRNAs/miRNAs interactions with verified roles in the control of oral cancer cells apoptosis." (PMID 35898889, 2022).
preeclampsia (7 papers, 2017 to 2023). Preeclampsia is a hypertensive disorder of pregnancy that is characterized by new-onset hypertension with proteinuria presenting after 20 weeks of gestation, and depending on mild or severe forms may initially present with severe headache, visual disturbances, and hyperreflexia. "Recent studies have shown that the abnormal expression of MEG3 in placental villi is closely associated with the preeclampsia and MEG3 can regulate the proliferative and invasive capacities of trophoblasts." (PMID 34238211, 2021). "The low level of MEG3 might be associated with failure in uterine spiral artery remodeling in preeclampsia by suppressing trophoblast cell migration, invasion and promoting apoptosis." (PMID 36310595, 2022). "Maternally expressed gene 3 (MEG3) is known to be involved in the pathogenesis of preeclampsia by inhibiting the migration and invasion of trophoblasts and promoting their apoptosis." (PMID 36310595, 2022). "It has been proposed previously that the expression of MEG3 was reduced in the placentas of preeclampsia patients at the trophoblast cell level." (PMID 36310595, 2022). "Combining with H19, MALAT-1, MEG3 and so on, the involvement of lncRNAs in preeclampsia will become more clear." (PMID 32194641, 2020). "Yu and coworkers (2018) work on MEG3 showed how MEG3 downregulation observed in preeclampsia correlates with an increase in adhesion molecule E-cadherin." (PMID 31212604, 2019). "Several lncRNAs, including MALAT1, HOXA11-AS and MEG3, had been demonstrated to be involved in the dysfunction of trophoblasts in RM diseases and pathogenesis of preeclampsia." (PMID 31572567, 2019). "Thus, we concluded that MEG3 alleviates preeclampsia progression not only by improving trophoblast dysfunction but also by inhibiting inflammatory activation." (PMID 36310595, 2022). "Maternally Expressed Gene 3 (MEG3) is expressed at low levels in placental villi during preeclampsia; however, its roles in unexplained recurrent spontaneous abortion (URSA) remain unclear." (PMID 34238211, 2021). "Cell-based assays further confirmed that MEG3 leads to the migration and invasion of trophoblasts, as well as the remodeling of uterine spiral arteries, by affecting the expression of NF-κB, Caspase-3, and Bax proteins in trophoblasts, which results in the onset of preeclampsia." (PMID 34238211, 2021). "Altogether, MEG3 protects from apoptosis, promotes migration and invasion by regulating endothelial-mesenchymal transition in trophoblast cells and therefore its downregulation possibly affects trophoblast invasion and placentation, playing a key role in preeclampsia." (PMID 31212604, 2019). "To establish the relationships between MEG3, β-Catenin, NLRP3 and the pathogenesis of preeclampsia, we first measured the expression levels of MEG3, β-Catenin and NLRP3 in placental tissues by qRT‒PCR." (PMID 36310595, 2022). "The current study revealed that MEG3 regulates trophoblast function and inflammation through the Wnt/β-Catenin/NLRP3 axis and provided new insights into the pathogenesis of preeclampsia." (PMID 36310595, 2022). "In this study, we detected lower expression levels of MEG3 and β-Catenin and higher expression of nod-like receptor pyrin domain-containing 3 (NLRP3) in placental tissues of pregnant women with severe preeclampsia (sPE) than in normal pregnancies." (PMID 36310595, 2022). "In our study, MEG3 and β-Catenin expression decreased and NLRP3 expression increased in HTR-8/SVneo cells stimulated by H/R, similar to the levels observed in the placental tissue of preeclampsia." (PMID 36310595, 2022).
renal fibrosis (7 papers, 2020 to 2024). A final common manifestation of a wide variety of chronic kidney diseases characterized by glomerulosclerosis and tubulointerstitial fibrosis. "DNMT1 regulates MEG3 expression by altering the methylation level of the MEG3 promoter in TGFβ1-induced renal fibrosis, thereby affecting the development of renal fibrosis." (PMID 36869378, 2023). "Studies have shown that DNMT1 enhances the level of methylation in CpG islands of the MEG3 promoter and thus restrains the expression of MEG3 in renal fibrosis." (PMID 37762249, 2023). "Additionally, it was previously demonstrated that miR-185 inhibitor significantly up-regulated DNMT1 expression in HK2 cell line, and by modulating DNMT1 thereby regulating MEG3 expression in TGF-β1-induced renal fibrosis." (PMID 38413914, 2024). "In diabetic nephropathy-induced renal fibrosis, silencing of lncRNA Meg3 inhibited LPS-induced production of CCL-2 and CXCL-2 cytokines, which ameliorated renal fibrosis in mice." (PMID 39113708, 2024). "Several lncRNAs, such as MEG3, H19 and HOTAIR, were reported to play important roles in mediating TGF-β and renal fibrosis." (PMID 32203053, 2020). "The overexpression of lncRNA MEG3 prevents TGF-β1-induced EMT, as shown by the elevated expression of E-cadherin and correspondingly inhibited protein level of N-cadherin and vimentin in HK2 transferred with overexpression plasmids of MEG3, and therefore, rescues TGF-β1-induced renal fibrosis." (PMID 32752143, 2020).
tongue squamous cell carcinoma (7 papers, 2014 to 2024). A squamous cell carcinoma that arises from the tongue. "Low MEG3 level was an independent prognostic indicator and was associated with poor survival of tongue SCC patients." (PMID 25045670, 2014). "The results from methylation-specific PCR revealed that the activation of Rb by the treatment of tongue squamous cell carcinoma (TSCC) cells with palbociclib increased unmethylated MEG3." (PMID 36851033, 2023). "Meg3 may play vital anti-tumor effects in tongue squamous cell carcinoma pathogenesis and represent potential prognostic biomarkers for stratification of patients with tongue squamous cell carcinoma." (PMID 25276098, 2014). "In addition, miR-26a and MEG3 expression were correlated in TSCC (Tongue Squamous Cell Carcinoma) cells and it has been postulated that this relationship depends on the ability of miR-26a to target DNMT3B in this model and thus prevent meg3 promoter methylation." (PMID 26992233, 2016).
type 1 diabetes (7 papers, 2012 to 2023). "It has been shown that the MEG3 gene region on the chromosome increases susceptibility to type 1 diabetes and that epigenetic modifications of the DLK1-MEG3 miRNA cluster are also altered in human type 2 diabetic islets." (PMID 37762249, 2023). "MEG3 and GPR183 were shown to be involved in the development of type 1 diabetes." (PMID 23145134, 2012). "While MEG3 expression was higher in islets compared to exocrine glands in BALB/c mice, islet expression of MEG3 was reduced in non-obese diabetic (NOD) mice, a model of type 1 diabetes, and db/db mice, a model of T2D." (PMID 28829354, 2017).
cerebral infarction (6 papers, 2016 to 2025). An ischemic condition of the brain, producing a persistent focal neurological deficit in the area of distribution of the cerebral arteries. "Down-regulation of MEG3 expression with the small interfering RANA plasmid si-MEG3 reduced cerebral infarct volume, reduced edema, and decreased neurobehavioral scores." (PMID 36275741, 2022). "Inhibiting the MEG3 expression improves the nerve injury and reduces the cerebral infarction area, blood-brain barrier permeability and neuronal apoptosis of MCAO rats." (PMID 34609952, 2021). "We next determined the pivotal role of MEG3 in cerebral infarction of MACO mice by animals injected with si-MEG3." (PMID 27642276, 2016). "Furthermore, treatment with nano polymer wrapped MEG3 shRNA conjugated with OX26 antibody was able to reduce the ischemic lesion volumes and enhance the angiogenesis in cerebral infarction area." (PMID 33613191, 2020).
fibrosis (6 papers, 2019 to 2024). the formation of excess fibrous connective tissue in an organ or tissue in a reparative or reactive process. "Reduced MEG3 expression was found in the livers of CCl4-treated mice and was negatively correlated with fibrosis progression." (PMID 39872125, 2024). "Another interesting lncRNA that was found to contribute to cardiac fibrosis and diastolic dysfunction is maternally expressed 3 (Meg3)." (PMID 38259314, 2023). "Hepatic MEG3 levels were reduced in human livers with fibrosis and cirrhosis." (PMID 39872125, 2024).
heart failure (6 papers, 2019 to 2024). Inability of the heart to pump blood at an adequate rate to meet tissue metabolic requirements. "By endogenously combining with SP1, lncR-AK045171 was capable of elevating the transcriptional activation of MEG3, resulting in alleviating heart failure." (PMID 36968595, 2023). "An in-depth investigation revealed that the lncR-Meg3/miR145/PDCD4 axis was engaged in diabetic cardiomyopathy, showing chaos in MEG3 expression and hastening heart failure." (PMID 36968595, 2023). "The finding that Meg3 expression is upregulated in clinical heart failure samples and controls the apoptosis of human cardiomyocites makes Meg3 particularly attracting as a therapeutic target." (PMID 32117954, 2019). "Signal transducer and activator of transcription 3 (STAT3) has been linked to a number of pathological processes in heart failure, including ECM accumulation, collagen generation, and inflammatory responses, all of which mediate MEG3 activation in various cardiovascular signal transduction pathways." (PMID 36968595, 2023). "Additionally, MEG3 demonstrated a strongly counter effect in cardiomyocytes generated from human stem cells and was upregulated in clinical heart failure samples." (PMID 37259407, 2023). "Correlation analysis in heart failure patients showed a significant favorable correlation between lnc-MEG3 and lnc-Chaer and a good positive correlation between mir361-5p and lnc-MEG3; however, a negative connection was seen between serum mir675 and mir361-5p, lnc-MEG3, and lnc-Chaer." (PMID 37259407, 2023).
Huntington disease (6 papers, 2013 to 2024). Huntington disease (HD) is a rare neurodegenerative disorder of the central nervous system characterized by unwanted choreatic movements, behavioral and psychiatric disturbances and dementia. "lncRNA MEG3 is related to a range of cancers, and neurodegenerative diseases including PD, Huntington’s disease (HD), and ischemic stroke." (PMID 38472261, 2024). "Upregulation of MEG3, TRIM4, and TCEAL5 were reported in different models of Huntington’s disease with an intracellular aggregation of mutant HTT, suggesting a link between PSEN1 ΔE9 and mutant HTT-induced transcriptomic changes." (PMID 36552881, 2022). "In Huntington's disease, for example, neural lncRNAs are upregulated in taurine upregulated 1 (TUG1) and in nuclear paraspeckle assembly transcript 1 (NEAT1) but are downregulated in maternally expressed 3 (MEG3)." (PMID 23843741, 2013).
Hypertension (6 papers, 2018 to 2025). The presence of chronic increased pressure in the systemic arterial system. "Therefore, our results provide a potential mechanism addressing the high-risk of hypertension in IVF offspring via MEG3 epigenetic regulation." (PMID 35047570, 2021). "lncRNA MEG3 is closely related to various pathologic effects of cardiomyocytes, fibroblasts and endothelial cells, and has great clinical application potential in the prevention and treatment of AS, MIRI, hypertension and HFLnc." (PMID 36523500, 2022).
pancreatic neuroendocrine tumor (6 papers, 2012 to 2023). Pancreatic endocrine tumor, also known as pancreatic neuroendocrine tumor (PNET), describes a group of endocrine tumors originating in the pancreas that are usually indolent and benign, but may have the potential to be malignant. "Meg3 was a cancer suppressor lncRNA which bound to chromatin on unique genomic regions in the c-Met gene in pancreatic neuroendocrine tumors (PNETs)." (PMID 37415734, 2023). "MEG3 was also reported to suppress pancreatic neuroendocrine tumor growth by down regulating miR-183/BRI3 axis." (PMID 31488093, 2019). "MEG3 serves as a ceRNA by sponging miR-183 to regulate the cell growth of pancreatic neuroendocrine tumor." (PMID 31531526, 2019).